CCL2 (C-C motif chemokine ligand 2)
Diseases named in the same sentence as CCL2 in open-access papers (continued):
Sharing a sentence is not in itself a finding about the gene and the disease.
breast cancer (continued). "The impact of this signaling pathway is further magnified by the direct interaction between β-catenin and the CCL2 promoter, which amplifies the characteristics of breast cancer stem cells, thus potentiating the aggressive nature of TNBC." (PMID 39286635, 2024). "CCL2 and CXCL12 SNPs are associated with breast cancer susceptibility in overweight and postmenopausal women, and the effect varies according to subtypes." (PMID 39703847, 2024). "By enzyme-linked immunosorbent assay (ELISA), 4T1 tumor-bearing mice showed elevated CCL2 serum levels compared to healthy mice (mean±s.e.m.=393±108.4 pg/ml), within range of those in patients with breast cancer (mean range=192-398 pg/ml)." (PMID 38973385, 2024). "One study evaluating breast cancer found that depleting tumor–derived CCL2 resulted in inhibition of metastases." (PMID 38716730, 2024). "The association between single nucleotide polymorphisms (SNPs) in the CCL2 and CXCL12 genes and the susceptibility to breast cancer was investigated using logistic regression models." (PMID 39703847, 2024). "Third, the current study observed the association between EGFR amplification, CCL2 upregulation and accumulation of TAM subtypes, which is supported by studies in GBM and breast cancer." (PMID 38515213, 2024). "In pancreatic, colon and breast cancers, CCL2 and CCR2 overexpression correlates with unfavorable prognosis." (PMID 38973385, 2024). "It has been found that inhibition of the CCL2/CCR2 signaling pathway with anti-CCL2 antibodies can block the recruitment of TAMs, and delay the progression of breast cancer." (PMID 39065562, 2024). "To examine the relevance of CCL2 in breast cancer, we examined the effects of conditioned medium from metastatic 4T1 mammary carcinoma cells." (PMID 38973385, 2024). "Metastasis-associated macrophages are functionally distinct from primary tumor TAMs and are also predominantly monocyte-derived and recruited by tumor cell-secreted CCL2 in the PyMT and other models of breast cancer that give rise to pulmonary metastases." (PMID 39588367, 2024). "In a study using a PyMT mammary tumor mouse model, inflammatory monocytes induced tumor cell metastasis and the molecular mediator was CCL2." (PMID 38786066, 2024). "CCL2 acts as an extracellular signal and facilitates migration, invasion, and survival in cancers such as breast cancer, prostate cancer, and hepatocellular carcinoma." (PMID 39138521, 2024). "Heat shock protein 60 (HSP60) on the surface of EVs released from breast cancer stimulates CCL2 expression in lung fibroblasts via the TLR2-MyD88-NF-κB signal pathway, leading to monocyte recruitment and suppression of T cell function." (PMID 38495881, 2024). "In breast cancers, overexpression of C-C chemokine ligand 2 (CCL2) correlates with unfavorable prognosis." (PMID 38973385, 2024). "We therefore added the analysis of plasma CCL2 and CXCL12 which confirmed the association with breast cancer." (PMID 39703847, 2024). "Previous studies have shown that EGFR from tumor cells can regulate the recruitment of macrophages by increasing CCL2 expression in glioblastoma and breast cancer." (PMID 38515213, 2024). "CCL2 siRNA treatment partially reduced CCL2 serum levels and significantly reduced the expression of CCL2 in 4T1 mammary tumors and skeletal muscle tissues." (PMID 38973385, 2024). "In this contest, the natural compound total glucosides of paeony (TGP) downregulates the expression of genes involved in the formation and function of TAMs via NF-κB/CCL2 ablation as well as the secretion of CCL2 in primary and metastatic breast cancer." (PMID 38397187, 2024). "In a study on a mouse model of breast cancer, for instance, the cessation of therapy which was based on blockade of CCL2/CCR2 axis, resulted in exacerbation of lung metastasis." (PMID 39003350, 2024). "Another approach using an adenovirus expressing IL-12 induced also a pro-inflammatory TME in a breast cancer model and an increased CCL2 expression." (PMID 39196415, 2024).
breast cancer (continued). "Elevated levels of CCL2 in peripheral blood indicate possible systemic effects of this chemokine in patients with breast cancer." (PMID 38973385, 2024). "In conclusion, the present study highlights that the CCL2 and CXCL12 SNPs are linked to breast cancer susceptibility, especially in overweight and postmenopausal Chinese women." (PMID 39703847, 2024). "Greater expression of the chemokine CCL-2 causes CRC to have a poor prognosis, whereas higher expression of the same chemokine causes breast cancer to have a favourable prognosis." (PMID 38339377, 2024). "The association between plasma CCL2 and CXCL12 with breast cancer was further examined in 72 patients and 75 controls." (PMID 39703847, 2024). "In that context, we have demonstrated that the expression of CCL2, a cytokine that is responsible for tumor-associated macrophage recruitment, is induced by HER2 overexpression in EGFR+ breast cancer cells." (PMID 39791720, 2024). "Because CCL2 is recruited in Gr1-positive inflammatory monocytes in the lung, the CCL2/CCR2 axis is also responsible for organ-specific metastasis of breast cancer." (PMID 37056561, 2023). "CCL2 is an M2 aggregation chemokine closely related to breast cancer, and anti-CCL2 treatment reduces the amount of M2 in tumors and limits the metastatic spread of cancer cells." (PMID 37542283, 2023). "Further, this study supports CCL2 as a mediator of these interactions that contributes to mammographic density and early breast cancer tumorigenesis through regulation of ECM, cancer gene pathways, and metabolic signalling." (PMID 37108548, 2023). "To further examine TNC and CCL2 interaction networks in the in vivo model of breast cancer, we assessed RNAseq data from mice grafted with TNC+ NT193 cells at both the early stage (3 weeks) and a later stage of the disease (11 weeks)." (PMID 37176074, 2023). "In an animal model of breast cancer, inhibiting CCL2 production by fibroblasts effectively suppressed tumor formation." (PMID 38273859, 2023). "As demonstrated in a mouse xenograft model of melanoma and breast cancer, MSCs secreted chemokines, namely CCL2, CCL5, CCL9, and CXCL10, which activated tumor cell migration and invasion, promoting the development of lung, bone, and lymph node metastases." (PMID 37686315, 2023). "Among the signaling molecules involved with MSC migration to the tumor site are CXCL12/CXCR4, CCL2 in Breast cancer, and SDF-1 in colorectal, prostate, and breast cancers." (PMID 36674525, 2023). "We uncover a correlation between TNC/CCL2 tissue levels in HER2+ breast cancer and examine the physical and functional interactions of these molecules in a murine disease model with tunable TNC levels and in in vitro cellular and cell-free models." (PMID 37176074, 2023). "Collectively, these results suggest that CXCR2-associated chemokines released from K2A-1 promote M2 macrophage polarization, which in turn secretes CCL2 to increase the resistance of breast cancer cells to paclitaxel." (PMID 37821959, 2023). "CXCR2-associated chemokines secreted by KDM2A-expressing CAFs stimulated M2 macrophage polarization, which in turn secreted CCL2 to increase paclitaxel resistance in breast cancer cells by activating CCR2 signaling." (PMID 37821959, 2023). "CC-chemokine ligand 2 (CCL2) is also capable of recruiting TAMs, and the cascade response triggered promotes breast cancer metastasis." (PMID 37542283, 2023). "Spleen macrophages carrying breast cancer tumors secrete higher levels of proinflammatory mediators CCL2, CXCL2, MMP-9, and CHI3L1 stimulating this increased secretion." (PMID 38003338, 2023). "Primary CAFs enhance the expression of chemokine (C‐C motif) ligand 2 (CCL2), which contributes to the stemness maintenance of breast cancer cells." (PMID 38045829, 2023). "In summary, our findings reveal that chronic bacterial infection can promote breast cancer lung metastasis by recruiting MHCIIhi neutrophils into the premetastatic lung via the chemokine CCL2." (PMID 37563136, 2023).
breast cancer (continued). "A previous study showed that CCL2 is an inflammatory mediator with proinflammatory activity in breast cancer." (PMID 36977240, 2023). "CCL2 plays a role in promoting the recruitment of monocytes to pre-metastatic niches in breast cancer." (PMID 36674955, 2023). "These polarized M2 macrophages, in turn, secreted CCL2, which contributed to the heightened paclitaxel resistance in breast cancer cells." (PMID 37821959, 2023). "These cells are associated with a poor prognosis and treatment response in breast cancer, and both TNC and CCL2 play a role in their biology." (PMID 37176074, 2023). "CCL22, for example, is only present at concentrations up to 1 ng/mL in ascites and tissue samples of ovarian cancer, as are CCL2 levels in the plasma of breast cancer patients." (PMID 36834542, 2023). "Previous studies show that reactive astrocytes secrete CCL2 in brain autoimmune diseases and, more relevantly to our current study, in primary brain glioma and breast cancer brain metastasis." (PMID 37149684, 2023). "Overall, these results suggest that chronic bacterial infection in the lung upregulates CCL2 expression, and in turn, CCL2 can partially recruit MHCIIhi neutrophils to the lung to promote lung metastasis of breast cancer." (PMID 37563136, 2023). "Neutralizing antibodies to CCL2 further inhibited the development of lung metastases in mice receiving a xenograft of the CCL2-expressing MDA-231 human breast cancer." (PMID 37373025, 2023). "These mice were cross-bred with PyMT mammary tumour mice to examine the role of CCL2 in tumorigenesis." (PMID 37108548, 2023). "Breast cancer cells induce the expression of cytokines (CCL2, CCL5, IL-1β, and IL-6) and immunomodulators (COX2, HIF-1α, VEGFα, and PD-L1) by cancer-associated adipocytes." (PMID 36670988, 2023). "Primary tumor–derived CCL2 can enhance breast cancer metastasis assisted by the recruitment of Ly6C+CCR2+ monocytes and retention of MAMs." (PMID 36976637, 2023). "In the PyMT mammary tumour model, CCL2 overexpressing mice exhibited increased macrophage infiltration and early tumorigenesis." (PMID 37108548, 2023). "In turn, TAMs were found to secrete CCL2 (C-C motif chemokine ligand 2) which further activates the PI3K/AKT/mTOR axis in tumor cells leading to tamoxifen resistance in breast cancer cells." (PMID 37900137, 2023). "Breast cancer cells were also found to upregulate osteoblast expression of CCL2, suggesting that breast cancer cells manipulate osteoid cells in the bone microenvironment to promote osteolysis and tumor progression." (PMID 37025604, 2023). "To assess any association between the expression of TNC and CCL2, we analyzed RNA sequencing data from 77 HER2+/ERBB2+ breast cancer patients available from The Cancer Genome Atlas." (PMID 37176074, 2023). "In patients with periodontitis, gingival disease facilitates lymph node metastasis, particularly in breast cancer, which is associated with increased expression of CCL5, CCL2, and CXCL5." (PMID 38139161, 2023). "Regarding vascularisation, CXCL12 and CCL2 are the most potent angiogenic chemokine, which enables the adequate oxygen supply required in metastatic breast cancer." (PMID 37680708, 2023). "Previous studies in our lab have demonstrated that CCL2 overexpression reduces tumour latency and tumour-free survival in a carcinogen-induced mammary tumour model." (PMID 37108548, 2023). "CCL2 participates in a variety of malignant tumors, such as breast cancer 178, lung cancer 179, and cervical cancer." (PMID 37497001, 2023). "Analysis of the TCGA database showed that the expression of CCL2 was significantly higher in breast cancer samples than in normal tissues, whereas the opposite was true in colorectal cancer samples." (PMID 37605148, 2023). "Signalling between CCR2 and its ligand CCL2 is related to the disease progression of various cancers, such as breast cancer and melanoma." (PMID 35999359, 2023).
breast cancer (continued). "Collectively, our results demonstrate that the aggressiveness of breast cancer with EGFR and HER2 co-expression is associated with CCL2-induced recruitment of TAMs." (PMID 36674955, 2023). "Tissue levels of both TNC and CCL2 are elevated in people with breast cancer, where the expression of each molecule individually correlates with disease progression." (PMID 37176074, 2023). "Adipocyte-derived CCL2 recruits macrophages into the breast cancer TME to form TAMs, which increase the secretion of PGE2." (PMID 36765683, 2023). "CCL2, which was already described to be involved in breast cancer as a potent TNC binder, leads to a decrease in monocyte cell migration." (PMID 37834140, 2023). "Building on the evidence that both TNC and CCL2 individually contribute to breast cancer progression and metastasis, this study aimed to formally examine the co-expression of these molecules and their physical and functional interactions." (PMID 37176074, 2023). "Our goal in this paper was to dissect any interplay between the matrix molecule TNC and the chemokine CCL2, with a focus on their impact on the myeloid compartment of breast cancer." (PMID 37176074, 2023). "Monocytes recruited by colony stimulating factor 1 (CSF1) and chemokine (C-C motif) ligand 2 (CCL2) secreted by breast cancer cells can develop into TAMs under various tumor microenvironmental signals." (PMID 36674955, 2023). "For other chemokines, according to recent research reports, CCL2 recruits monocytes to generate vascular endothelial growth factors, thereby facilitating breast cancer cell extravasation." (PMID 38075694, 2023). "In summary, tumor-derived TNC dominates the effect on myeloid cell polarization and tumor growth in the in vivo and cellular models of breast cancer that we have used in this study, as well as controls CCL2 transcription in tumor cells." (PMID 37176074, 2023). "In murine mammary tumors, CCL2 secretion was also reported to indirectly support metastasis by promoting inflammatory monocyte recruitment." (PMID 35159113, 2022). "In the current study, we demonstrate that the lncSNHG5-ZNF281 signaling axis in breast CAFs plays a central role in lung PMN formation in breast cancer by regulating CCL2 and CCL5 expression." (PMID 36438499, 2022). "CCL2/CCR2 signaling was reported to foster metastasis and prolong the survival of tumor-bearing mice, and CCL2 expression and macrophage infiltration are correlated with a poor prognosis and metastatic disease in human breast cancer." (PMID 35707538, 2022). "High levels of CCL2 expression in various types of tumors are also associated with poor prognosis; for example, the increased level of CCL2 expression is related to poor prognosis in breast cancer patients." (PMID 35464849, 2022). "CCL2/CCR2 signalling has been shown to promote the activation of the CCL3 (MIP-1α)/CCR1 signalling cascade in breast cancer metastasis to the lung, leading to the retention of metastasis associated macrophages and colony growth." (PMID 36241867, 2022). "Recent work in PD-L1 inhibitor resistant triple negative BC patients revealed that inhibition of TG2, restored T cell-dependent cytotoxicity by inhibiting expression of PD-L1 and CCL2 in PD-L1+ breast cancer cells." (PMID 35681474, 2022). "Conversely, miR-375 induced CCL2 expression in human breast cancer cell lines and was transferred to TAMs in apoptotic tumor bodies, directly regulating their polarization." (PMID 36248881, 2022). "To understand how CCL2/CCR2 signaled in breast cancer cells in the context of other oncogenic receptors, we used candidate and unbiased profiling approaches." (PMID 35405500, 2022). "Through analysis of data obtained from reverse phase protein profiling in a previous study, we found that CCL2 treatment of MCF10CA1d breast cancer cells enhanced phosphorylation of MET receptors, which was reduced in CCR2 knockout cells." (PMID 35405500, 2022).
breast cancer (continued). "Future studies would involve in-depth isotope tracing studies on breast cancer cell lines and tissues to determine the contributions of glucose and glutamine to CCL2/CCR2- and MET-mediated metabolism during DCIS progression." (PMID 35405500, 2022). "As a result, studying the function of CCL2 in the progression of breast cancer can provide new ideas for the screening, diagnosis, and treatment of breast cancer." (PMID 36403055, 2022). "CCL2 and CXCL12 produced by breast cancer-associated fibroblasts and tumor cells promote the recruitment and differentiation of monocytes into immunosuppressive TAMs." (PMID 35309358, 2022). "CCL2 can lead to the activation and accumulation of Tregs, thus suppressing antitumor immunity in breast cancer tissues." (PMID 36077785, 2022). "Recent studies suggest that CCL2 affects trastuzumab efficacy in breast cancer and induces trastuzumab resistance in HER2+ gastric cancer." (PMID 36077785, 2022). "Our finding regarding the interdependence of β-catenin and CCL2 is supported by a recent study showing that the β-catenin-CCL2 feedback loop mediates crosstalk between breast cancer stem cells and macrophages." (PMID 35562953, 2022). "A recent study demonstrated that a β-catenin-CCL2 feedback loop mediates crosstalk between cancer cells and macrophages in breast cancer stem cells." (PMID 35562953, 2022). "Specifically, PYK2 ablation inhibits Notch1 signaling and consequently reduces CCL2 secretion by breast cancer cells, and concurrently reduces the levels of CCR2, CXCR4, IL‐4Rα, and Stat6 activation in macrophages." (PMID 35092356, 2022). "For CCL2-directed inhibition therapy, termination of the drug regiment adversely enhanced metastatic progression and decreased survival in mouse breast cancer models." (PMID 36275727, 2022). "Inhibition of CCR2/CCL2 with a CCL2 blocking antibody inhibited the infiltration of monocytes and metastatic seeding of breast cancer cells in mice." (PMID 33603130, 2022). "And CCL2 was ranked the first among them, which has been reported to be significantly correlated with macrophage infiltration and poor prognosis in human breast cancer." (PMID 36038549, 2022). "One previous Mendelian randomization analysis on cytokines found an association between genetically predicted CCL2, CCL4, and GROα and breast cancer." (PMID 36685922, 2022). "CRISPR knockout and pharmacologic inhibition of MET revealed that CCL2/CCR2-induced breast cancer cell proliferation, survival, migration and glycolysis through MET-dependent mechanisms." (PMID 35405500, 2022). "Extracellular flux analysis and biochemical assays revealed that CCL2/CCR2 signaling in breast cancer cells enhanced glycolytic enzyme expression and activity." (PMID 35405500, 2022). "For example, the overexpression of CCL2 enhances the outgrowth, invasion, and metastasis of the 4T1 murine mammary cancer cell line which is one of the most widely used breast cancer models." (PMID 36685497, 2022). "The vast majority of studies have acknowledged the altered expression of CCL2 in different cancers, e.g., prostatic cancer, colorectal cancer, and breast cancer." (PMID 35408440, 2022). "CCL2 binds to CCR2 on the surface of metastasis-associated macrophages, causing the macrophages to generate CCL3 and increasing breast cancer lung metastasis." (PMID 36403055, 2022). "Phospho-protein array profiling revealed that CCL2 stimulated phosphorylation of MET receptor tyrosine kinases in breast cancer cells." (PMID 35405500, 2022). "For instance, tumor cells of lung metastasis (derived from breast cancer) produce CCL2, recruiting and retaining monocytes/macrophages, likewise fibrocytes that prepare the premetastatic niche for melanoma cells by the exact mechanism." (PMID 35664746, 2022). "Estrogen up-regulates CCL2 expression in ER+ breast cancer cells through the Twist/PI3K/AKT/NF-κB signaling pathway." (PMID 36403055, 2022).